PHYHIPL (phytanoyl-CoA 2-hydroxylase interacting protein like)
Description:
May play a role in the development of the central system.
Synonyms: KIAA1796; Em:AC025038.1
Tractability: PROTAC: its protein half-life has been measured.
Gene: Protein-coding gene on chromosome 10 (59,176,643 to 59,247,774, forward strand). Ensembl gene ENSG00000165443.
Subcellular location (Human Protein Atlas): Cytosol
Gene Ontology:
Molecular function: protein binding
Cellular component: cytoplasm
Genetic constraint (gnomAD): Loss-of-function variants: 5 observed, 24.79 expected, observed/expected ratio (o/e) 0.2, 90% interval 0.1 to 0.42. The upper end of that interval is the gene's LOEUF score, 0.42, which puts it in group 1 of 6, group 1 being the genes least tolerant of losing a copy. Missense variants: 320 observed, 423.55 expected, observed/expected ratio (o/e) 0.76, 90% interval 0.69 to 0.83. Synonymous variants: 134 observed, 143.94 expected, observed/expected ratio (o/e) 0.93, 90% interval 0.81 to 1.08.
Homologues: Orthologues: chimpanzee PHYHIPL (99% identical), macaque PHYHIPL (99% identical), dog PHYHIPL (99% identical), pig PHYHIPL (98% identical), rabbit PHYHIPL (98% identical), mouse Phyhipl (97% identical), rat Phyhipl (97% identical), tropical clawed frog phyhipl (91% identical), guinea pig PHYHIPL (89% identical), zebrafish phyhiplb (85% identical), zebrafish phyhipla (76% identical), Caenorhabditis elegans T10H4.4 (25% identical), and 5 more. Paralogues in human: PHYHIP (66% identical).
Diseases named in the same sentence as PHYHIPL in open-access papers:
PHYHIPL is named in the same sentence as 8 diseases in open-access papers, as found by Europe PMC text mining. Sharing a sentence is not in itself a finding about the gene and the disease. The quoted sentences say what the papers report.
glioblastoma (4 papers, 2021 to 2022). The most malignant astrocytic tumor (WHO grade IV). "Previous findings from TCGA database reported that the downregulation of PHYHIPL is associated with poor OS, demonstrating that this gene is involved in the development of Glioblastoma multiforme (GBM)." (PMID 34178621, 2021). "PHYHIPL, a paralog of the phytanoyl-CoA hydroxylase-interacting protein, is altered in glioblastoma multiforme, where its function remains unknown, and has been proposed as a therapeutic target gene." (PMID 35159257, 2022). "PHYHIPL gene expression is altered in global ischemia and glioblastoma multiforme." (PMID 33712038, 2021).
prostatic small cell carcinoma (1 paper, 2021). "Phytanoyl-CoA 2-hydroxylase-interacting protein-like gene (PHYHIPL), a protein-encoding gene, may correlate with the prostatic small cell carcinoma." (PMID 34178621, 2021).
tumor (5 papers, 2021 to 2024). "Our study identified novel iCCA‐associated genes FAM171A1, ONCUT1 and PHYHIPL and implied their tumour suppressing roles and prognosis values." (PMID 34013637, 2021). "Similarly, the expression of FAM171A1 (family with sequence similarity 171 member A1), ONECUT1 (one cut homeobox 1), and PHYHIPL (phytanoyl-CoA 2-hydroxylase-interacting protein-like) decreased with tumor stage and was associated with survival." (PMID 39199659, 2024). "As a result, we identified CDH3, EFHD2 as tumour‐promoting genes, and ONECUT1, PHYHIPL as tumour suppressing genes." (PMID 34013637, 2021). "Consistent with the trend of overall expression of hub genes, expression of FAM171A1, ONECUT1 and PHYHIPL decreased across the tumour stage." (PMID 34013637, 2021). "Moreover, our findings revealed key pathways mediated by suppression of ONECUT1 and PHYHIPL for the tumour progression." (PMID 34013637, 2021). "Moreover, we further analyzed the difference of expression levels of four genes in tumor and normal tissues and found that the expression level of PHYHIPL (P = 0.002) in CRC tissues is lower than that of normal tissue." (PMID 34178621, 2021). "The results showed that six genes (BOLA3-AS1, AC124067.4, AL161772.1, SALL4, PHYHIPL, and TNFSF11) were significantly associated with the COAD immune subtype (p < 0.05), indicating that these seven genes could modulate tumor immune functions at the genetic level." (PMID 34746134, 2021). "Finally, significant negative associations between expression of EFHD2, PHYHIPL and promoter DNA methylation were detected, and alterations of DNA methylation were correlated with tumour survival." (PMID 34013637, 2021). "Key hub genes SLC2A1, CDH3 and EFHD2 showed increased expression across the tumour stage and were correlated with poor survival, whereas decrease of FAM171A1, ONECUT1 and PHYHIPL was correlated with better survival." (PMID 34013637, 2021). "Given that activation of these pathways were involved in tumour development, these observations indicate that down‐regulation of ONECUT1 and PHYHIPL can induce activation of these key pathways to promote iCCA progression." (PMID 34013637, 2021).
cancer (3 papers, 2020 to 2021). A tumor composed of atypical neoplastic, often pleomorphic cells that invade other tissues. "To comprehensively understand these three lncRNAs (BOLA3-AS1, AC124067.4, and AL161772.1) and four target RNAs (NINL, SALL4, TNFSF11, PHYHIPL), we performed differential expression, cancer stemness, immune subtype, TME infiltration, and drug sensitivity analyses." (PMID 34746134, 2021). "Among these genes, three (BATF, PHYHIPL, and RBP1) have been reported as cancer-associated genes." (PMID 34178621, 2021). "PHYHIPL (or PAHX-AP1) has mostly been described in the context of neuronal cells, but no role in cancer has been described." (PMID 31949161, 2020).
PHYHIPL also shares sentences with these, for which no sentence is quoted: cervical cancer (1 paper); glioma (1); non-small cell lung carcinoma (1); tongue squamous cell carcinoma (1).